SIRT3 (sirtuin 3)
Diseases named in the same sentence as SIRT3 in open-access papers (continued):
Sharing a sentence is not in itself a finding about the gene and the disease.
Alzheimer disease (40 papers, 2012 to 2025). A progressive, neurodegenerative disease characterized by loss of function and death of nerve cells in several areas of the brain leading to loss of cognitive function such as memory and language. "Studies have shown that SIRT3 is closely associated with the regulation of oxidative stress-related mitochondrial damage in cardiac ischemia-reperfusion injury and Alzheimer's disease." (PMID 36092157, 2022). "We have reported that deletion of Sirt3 gene leads to downregulation of metabolic enzymes, mitochondrial dysfunction and neuroinflammation in the brain, the main causes of Alzheimer’s disease." (PMID 34393764, 2021). "We have earlier demonstrated that deletion of Sirt3 gene leads to downregulation of metabolic enzymes, mitochondrial dysfunction and neuroinflammation in the brain, the major causes of Alzheimer’s disease (AD)." (PMID 34393764, 2021). "Sirt-3 is an important regulator of mitochondrial function and cellular energy homeostasis, whose function is associated with aging and various pathologies such as Alzheimer’s disease, Parkinson’s disease, cardiovascular diseases, and cancers." (PMID 38612678, 2024). "Decreased Sirt3 levels have been implicated in the development of neurodegenerative disorders such as amyotrophic lateral sclerosis, Parkinson’s disease (PD), Alzheimer’s disease (AD), and probably Huntington’s disease, while its role in cancer is not clear yet." (PMID 38612678, 2024). "SIRT3 is associated with anxiety in mice with Alzheimer's disease." (PMID 35372451, 2022). "Interestingly, Sirt3 co-expressed genes in both tissues were associated with focal adhesion, myelin sheath, Huntington’s disease, Parkinson’s disease and Alzheimer’s disease." (PMID 30871457, 2019). "Evidence from animal study demonstrated that exogenous upregulation of SIRT3 effectively ameliorated cognitive dysfunction in transgenic mouse models of Alzheimer’s disease (AD)." (PMID 40969935, 2025). "Aloe‐emodin enhances SIRT3 expression through such a pathway, protecting hippocampal neurons among Alzheimer's disease mice." (PMID 40125832, 2025). "SIRT3 is an important protective player in sustaining mitochondrial function among cells modeled for Alzheimer's disease." (PMID 40125832, 2025). "The p‐AMPK and SIRT3 levels in Alzheimer's disease (ad) mice were much lower than those in the WT group (p < 0.01)." (PMID 40125832, 2025). "HKL improves cognitive performance in Alzheimer's disease mice by activating the SIRT3‐mediated mitochondrial autophagy." (PMID 39097923, 2024). "In Alzheimer disease, honokiol increased SirT3 expression levels and activity, which in turn markedly improved ATP production and weakened mitochondrial ROS production, rescuing memory deficits." (PMID 38129330, 2023). "Contrary to our findings, a reduced SIRT3 expression was observed in postmortem brain slices of Alzheimer’s disease (AD) patients, which was paralleled with increased tau acetylation levels." (PMID 37408218, 2023). "Both basic pathomechanisms underlying Alzheimer’s disease and some premises for stipulating a possible preventive role of some sirtuins, especially SIRT1 and SIRT3, protective against Alzheimer’s disease-related pathology, are discussed in this article." (PMID 36045741, 2022). "A recent study in APP mutant model of Alzheimer’s disease (AD) has shown that IF reduced hippocampal neuron hyperexcitability and ameliorated cognitive deficits in a SIRT3-dependent manner." (PMID 35562171, 2022). "The role of Sirt3 has been investigated in several diseases, such as Alzheimer's disease, cardiovascular diseases, and renal diseases." (PMID 33005288, 2020). "The available evidence indicates that Sirt3 is involved in cognition decline of Alzheimer’s disease." (PMID 31652451, 2019).
Alzheimer disease (continued). "This review article provides a comprehensive review on numerous (noteworthy) molecular functions of SIRT3 and its effect on cancer cells and various diseases including Huntington's disease, amyotrophic lateral sclerosis, and Alzheimer's disease." (PMID 27686535, 2017). "The goal of this review is to summarize emerging data supporting a neuroprotective action of SIRT3 against Alzheimer’s disease, Huntington’s disease, Parkinson’s disease, and amyotrophic lateral sclerosis." (PMID 24046746, 2013). "Here we investigate a role for CNS Sirt3 in mitochondrial responses to reactive oxygen species (ROS)- and Alzheimer’s disease (AD)-mediated stress." (PMID 23139766, 2012). "Moreover, OA suppressed oxidative stress by regulating the stanniocalcin-1 pathway in a cell model of Alzheimer’s disease treatment, as well as repressed oxidative stress via the SIRT3/NF-κB axis in an in vitro osteoarthritis cell model." (PMID 35056059, 2021). "Recently, SIRT3 has been shown to be strongly involved in the regulation of oxidative stress-related mitochondrial damage in neurodegenerative diseases, such as Parkinson’s disease (PD) and Alzheimer’s disease (AD)." (PMID 33541361, 2021). "SIRT1 affects progression of Alzheimer’s disease through interactions with FOXO3a and SIRT3." (PMID 33806509, 2021). "SIRT3 activators that could improve Alzheimer’s disease found in nearly a decade." (PMID 40969935, 2025). "Other studies reported that the extracellular Alpha‐synuclein (ASN) or transcription factor NRF2 could also regulate the SIRT3 expression in Alzheimer's disease, whether these were involved in the change of SIRT3 of postoperative delirium in mice need further investigation in the following studies." (PMID 39138637, 2024). "Besides, considering that MAM coupling is implicated as an earlier event in the process of Alzheimer’s disease-type pathologies, further investigation is required to understand the mechanisms underlying aberrant MAM formation and the potential role of SIRT3 in other types of cognitive impairment." (PMID 37481555, 2023). "High expressions of SIRT3 in cerebral cortical and hippocampal cells could benefit for treating anxiety and cognitive disorders, which was found as considerable overlap mechanisms by which IF and exercise enhance brain function of Alzheimer’s Disease patients." (PMID 36925956, 2023). "miR-298 exhibits further biological relevance through its association with sirtuin-3 (SIRT3), which impacts mitophagy, reactive oxygen species, and toxic protein accumulation, known mechanisms involved in ALS, Alzheimer’s disease, and Parkinson’s disease pathogenesis." (PMID 34776863, 2021). "Interestingly, SIRT3 acts as a pro-survival factor in neurons exposed to excitotoxic injury and recent studies demonstrate a neuroprotective effect of SIRT3 in cell culture models of stroke, Huntington’s disease (HD), and Alzheimer’s disease (AD)." (PMID 31931835, 2020). "Here, we substantiated this hypothesis through activating SIRT3 with kaempferol, a small polyphenolic molecule widely found in plants, which has been shown in several studies to ameliorate a variety of neurodegenerative diseases including Alzheimer's disease and cognitive impairment." (PMID 38267829, 2024). "Our bioinformatics analysis revealed four key differential genes—ASS1, HDAC2, SIRT3, and VEGFA—as Co-DEGs in patients with Alzheimer’s disease (AD) and OSA." (PMID 39081807, 2024). "For example, honokiol, a natural compound found in the bark of magnolia trees, upregulates PGC-1α protein expression by enhancing the protein expression level of SIRT3 and AMPK phosphorylation in Alzheimer’s disease-like cells." (PMID 33546195, 2021). "Neurodegenerative disorders, such as Alzheimer’s disease (AD), Parkinson’s disease (PD), Huntington’s disease (HD), amyotrophic lateral sclerosis (ALS), and multiple sclerosis (MS), may benefit from a thorough and in-depth investigation of Sirt3." (PMID 37238605, 2023).
Alzheimer disease (continued). "Sirtuins contains of SIRT1, SIRT3, and SIRT6 in saliva can be an extra technique for non-invasive intravital diagnosis of Alzheimer’s disease in elderly individuals." (PMID 39484071, 2024).
myocardial infarction (40 papers, 2013 to 2026). Gross necrosis of the myocardium, as a result of interruption of the blood supply to the area, as in coronary thrombosis. "Studies indicate that Sirtuin 3 activator theacrine improved heart function after estrogen-deficient mice myocardial infarction by boosting sirtuin 3 levels and modulating the β-catenin/PPARγ signaling pathway." (PMID 39256355, 2024). "Sirt3-deficient mice showed blunted recovery from myocardial infarction and brain ischemic stroke due to their impaired VEGF-dependent angiogenic capacity." (PMID 37816025, 2023). "A previous study showed that Sirt3 deficiency increased myocardial infarct size after ischemia and impaired the recovery of contractile function following reperfusion." (PMID 30042676, 2018). "After 6 h of resuscitation, left ventricular function, myocardial infarction, oxidative stress markers, inflammatory cytokine release, mitochondrial function, necroptosis-associated protein expression, and both Sirt3 expression and enzymatic activity were assessed." (PMID 40635895, 2025). "A reduction in SIRT3 expression has been observed in leukocytes from individuals with myocardial infarction, suggesting that SIRT3 may protect against thrombotic complications associated with myocardial infarction." (PMID 37298289, 2023). "Moreover, these abnormalities of SIRT3 deficient BMCs limited the BMCs-mediated cardiac repair in post-myocardial infarction (MI) mice." (PMID 30873415, 2019). "Myocardial cells at the periphery of myocardial infarction showed decreased expression of sirtuin 3 and peroxisome proliferator-activated receptor γ (PPARγ), but dramatically enhanced expression of β-catenin." (PMID 39256355, 2024). "SIRT3 upregulation is related to autophagy activation and is a drug target to attenuate mitochondrial dysfunction in myocardial infarction." (PMID 39872885, 2024). "It has been reported that miR-133 protects the heart by actually ameliorating cardiac injury, reducing myocardial infarct size, and inhibiting cardiomyocyte apoptosis, inflammation, and oxidative stress through the SIRT3/AMPK pathway." (PMID 38271362, 2024). "It has been demonstrated that Sirt3 protects hearts from myocardial infarction by the upregulation of autophagy and improving mitochondrial biogenesis." (PMID 37760018, 2023). "In a myocardial infarction model, Sirt3 attenuated cardiac injury post-myocardial infarction by improving microvascular function." (PMID 37760018, 2023). "In the mouse model of acute myocardial infarction, polydatin can activate Sirt3, up-regulate autophagic flux of myocardial cells and improve mitochondrial dysfunction, so as to protect myocardial cells from myocardial infarction injury." (PMID 37063954, 2023). "Polydatin, a polyphenol isolated from Polygonium cuspidatum has been shown to ameliorate myocardial infarction in cardiomyocytes through a SIRT3-dependent increase in mitochondrial biogenesis and autophagy and a decrease in apoptosis." (PMID 35369299, 2022). "Theacrine activated SIRT3 and repress myocardial fibrosis and apoptosis after myocardial infarction in ovariectomized mice, resulting in improvement of the cardiac function of ovariectomized mice with myocardial infarction." (PMID 33392238, 2020). "Cardiomyocyte-specific overexpression of SirT3 reduces myocardial infarct size by inhibiting cardiomyocyte death and preventing infarct zone extension." (PMID 32721927, 2020). "Following myocardial infarction in adult rats in vivo, infarct size decreased and cardiac function was significantly enhanced after cell transplantation with SIRT3 overexpressed O‐hMSCs." (PMID 30091830, 2018). "It is possible that SIRT3 expression in cardiac muscle in the myocardial infarction model is more sensitive to changes in response to HIIT." (PMID 29875683, 2018).
myocardial infarction (continued). "Recent studies have demonstrated that increased levels of SIRT-3 protect the kidney from cisplatin nephrotoxicity, whereas the knockout of SIRT-3 led to more severe damage after myocardial infarction." (PMID 30360430, 2018). "Wild type and Sirt3 knockout (Sirt3 KO) mice were treated with streptozotocin (STZ) to induced hyperglycemic DM model followed by myocardial infarction by ligation of Left Anterior Descendant (LAD) artery." (PMID 29167823, 2015). "According to previous studies, SIRT3 could alleviate myocardial infarction by inhibiting AMPK-Drp1-mediated mitochondrial fission." (PMID 36192726, 2022). "Furthermore, SIRT3 inhibited myocardial fibrosis and apoptosis after myocardial infarction by regulating the ß-catenin/PPARγ signal pathway." (PMID 34422410, 2021). "Interestingly, genetic ablation of SIRT3 markedly eliminated the hypertrophic preconditioning effects, as evidenced by expanded myocardial infarct size, exacerbated cardiomyocyte apoptosis and worsened cardiac function in I/R mouse hearts." (PMID 33973685, 2021). "Polydatin, a monocrystalline and a polyphenolic drug extracted from the traditional Chinese herb Polygonum cuspidatum, protects cardiomyocytes against myocardial infarction injury by upregulating autophagy and improving mitochondrial biogenesis via SIRT3 activity." (PMID 29643974, 2018). "In addition, our data showed no change in SIRT3 content in cardiac muscle, which is inconsistent with previous findings of upregulation of cardiac muscle SIRT3 expression in a rodent model of myocardial infarction following HIIT." (PMID 29875683, 2018). "SIRT3 is necessary for bone marrow cell-mediated cardiac repair in post-myocardial infarction." (PMID 27078640, 2016). "This study investigated whether Sirt3 is necessary for bone marrow cell (BMC)-mediated cardiac repair in post-myocardial infarction (MI)." (PMID 25192254, 2014). "Interestingly, SIRT3 overexpression restored cardiac function in mice after myocardial infarction." (PMID 36187338, 2022). "For example, in mouse models of cardiac dysfunction, polydatin could protect cardiomyocytes from myocardial infarction injury by improving mitochondrial biogenesis, enhancing autophagy, and inhibiting apoptosis, but these effects were largely abolished by SIRT3 knockout." (PMID 35453351, 2022). "We further investigated the efficacy of cell transplantation therapy when SIRT3‐modified O‐hMSCs were injected into the infarct region of the heart using a rat myocardial infarction (MI) model." (PMID 30091830, 2018).
myocardial ischemia (37 papers, 2017 to 2025). A disorder of cardiac function caused by insufficient blood flow to the muscle tissue of the heart. "Through the activation of the SIRT3/FOXO3a signaling pathway, obese mice that were given extended resveratrol demonstrated a decrease in the damage caused by myocardial ischemia." (PMID 40191425, 2025). "In particular, decreased SIRT3 contributes to the susceptibility of aged hearts to myocardial ischemia/reperfusion (MI/R) injury." (PMID 29849892, 2018). "Studies have demonstrated that SIRT3 protects against acute myocardial ischemia injury while SIRT3 deficiency significantly inhibits angiogenesis and cardiac functional recovery following MI." (PMID 29849892, 2018). "For example, Ginsenoside Rh1 active SIRT3 to suppress oxidative stress and mitochondria damage to protect against myocardial ischemia-induced mitochondrial dysfunction." (PMID 40533778, 2025). "By promoting the SIRT3/FOXO3a signaling pathway, resveratrol shields obese animals against the damaging effects of cardiac ischemia." (PMID 41567643, 2025). "On the other hand, DEX has been shown to ameliorate cardiac ischemia/reperfusion injury that can be improved by promoting autophagy via the AMPK/SIRT3 signaling pathway activation, indicating the relationship between DEX and SIRT3 signals." (PMID 40635757, 2025). "We demonstrated the critical roles of endothelial SIRT3 in regulating coronary microvascular dysfunction, diastolic dysfunction, and cardiac recovery post‐myocardial ischemia." (PMID 39425510, 2024). "Our previous studies have shown that decreased SIRT3 levels cause coronary microvascular dysfunction, impaired coronary flow reserve (CFR), diastolic function, and cardiac recovery post‐myocardial ischemia." (PMID 39425510, 2024). "Age‐related sensors Sirtuin1 (SIRT1) and Sirtuin3 (SIRT3) play an essential role in the protective response upon myocardial ischemia and/or reperfusion (I/R)." (PMID 37537789, 2023). "In acute myocardial ischemia, Sirtuin 3 (SIRT3) downregulation promotes Drp1 activation, thereby activating caspase-9 and triggering apoptosis in cardiomyocytes to accelerate myocardial fibrosis and inflammation." (PMID 37833768, 2023). "For example, muscone attenuates myocardial ischemia-reperfusion injury by inhibiting oxidative stress and enhancing SIRT3." (PMID 38158445, 2023). "Further study demonstrated that DHY treatment increased SIRT3 level in the heart of myocardial ischemia/reperfusion mice." (PMID 32933152, 2020). "Activation of Sirt3 mediates the beneficial effects of various agents that protect against myocardial ischemia/reperfusion." (PMID 31885797, 2019). "Sirt3 has played a key role in a variety of cellular processes, which has a protective effect in myocardial ischemia and neurodegenerative diseases." (PMID 31729962, 2019). "Extended resveratrol consumption may protect obese mice from myocardial ischemia damage by restoring intracellular redox equilibrium through the activation of the SIRT3/FOXO3a signaling pathway." (PMID 40191425, 2025). "The dynamic network of SIRT1/SIRT3 in response to myocardial ischemia and reperfusion stress." (PMID 37537789, 2023). "Kyn could induce macrophage cells inflammation and oxidative stress by activating the Sirt3-acSOD2/IL-1β pathway following myocardial ischemia injury." (PMID 36405744, 2022). "Kyn may act as a signaling molecule to activate the Sirt3-acSOD2/IL1β pathway leaded to macrophage cells inflammation and oxidative stress after myocardial ischemia injury." (PMID 36405744, 2022). "Notably, ROS and SIRT1/SIRT3 are major regulators of substrate metabolism, which modulates the inflammatory responses during myocardial ischemia and reperfusion." (PMID 32933202, 2020).
myocardial ischemia (continued). "Here, we hypothesized that resveratrol may protect against myocardial ischemia/reperfusion injury (MIRI) through the target of Sirt1/Sirt3 on mitochondrial dynamics, cardiac autophagy, bioenergetics and oxidative damage in hypoxia/reoxygenation (H/R)-induced neonatal rat cardiomyocytes." (PMID 36080311, 2022). "A study of a myocardial ischemia/reperfusion model demonstrated that inhibition of AMPK significantly reduced the expressions of PGC-1α and SIRT3, impaired mitochondrial function, increased mitochondrial oxidative damage, and promoted myocardial injury." (PMID 33946939, 2021).